PLEKHG7 (pleckstrin homology and RhoGEF domain containing G7)
Synonyms: C12orf74; FLJ46688
Tractability: PROTAC: ubiquitination databases record sites on it.
Gene: Protein-coding gene on chromosome 12 (92,702,843 to 92,772,455, forward strand). Ensembl gene ENSG00000187510.
Subcellular location (Human Protein Atlas): Centrosome
Gene Ontology:
Molecular function: protein binding; guanyl-nucleotide exchange factor activity
Genetic constraint (gnomAD): Loss-of-function variants: 56 observed, 59.26 expected, observed/expected ratio (o/e) 0.94, 90% interval 0.76 to 1.18. The upper end of that interval is the gene's LOEUF score, 1.18, which puts it in group 5 of 6, group 1 being the genes least tolerant of losing a copy. Missense variants: 627 observed, 647.46 expected, observed/expected ratio (o/e) 0.97, 90% interval 0.91 to 1.03. Synonymous variants: 253 observed, 253.48 expected, observed/expected ratio (o/e) 1, 90% interval 0.9 to 1.11.
Homologues: Orthologues: rabbit PLEKHG7 (82% identical), chimpanzee PLEKHG7 (75% identical), macaque PLEKHG7 (73% identical), guinea pig PLEKHG7 (54% identical), tropical clawed frog plekhg7 (53% identical), zebrafish plekhg7 (41% identical), Caenorhabditis elegans rhgf-2 (17% identical). Paralogues in human: PLEKHG5 (20% identical).
Diseases named in the same sentence as PLEKHG7 in open-access papers:
PLEKHG7 is named in the same sentence as 6 diseases in open-access papers, as found by Europe PMC text mining. Sharing a sentence is not in itself a finding about the gene and the disease. The quoted sentences say what the papers report.
tumor (2 papers, 2014 to 2025). "In our analysis eight new candidate tumor suppressor genes were identified, OXSR1 (3p22.2), BSG(19p13.3), NT5E(6q14.3), PLEKHG7(12q22), CMTM8(3p22.3), NETO2(16q12.1), ODZ3(4q35.1) and ERBB4(2q34)." (PMID 25551557, 2014). "Besides the known tumor suppressor genes DOCK5 and PTEN, genes OXSR1, BSG, NT5E, PLEKHG7,CMTM8, NETO2, ODZ3, and ERBB4 adhered to our criteria and were qualified as novel candidate tumor suppressor genes." (PMID 25551557, 2014).
PLEKHG7 also shares sentences with these, for which no sentence is quoted: cervical cancer (1 paper); cervical tumors (1); coronary artery disease (1); lung adenocarcinoma (1); osteosarcoma (1).